CENPF (centromere protein F)
Diseases named in the same sentence as CENPF in open-access papers (continued):
Sharing a sentence is not in itself a finding about the gene and the disease.
lentivirus infection (1 paper, 2021). Virus diseases caused by the Lentivirus genus. "After shCENPF lentivirus infection, the expression levels of CENPF mRNA were significantly decreased in the shCENPF group of A549 cells." (PMID 33390818, 2021). "The qRT-PCR results revealed that CENPF expression was downregulated for nearly 80% in LUAD cells by the shCENPF lentivirus infection compared with shCtrl (P = 0.007)." (PMID 33390818, 2021).
liver cirrhosis (1 paper, 2021). "In the present study, the level of serum CENPF autoantibody showed significant differences between the different stages of HBV-related liver cirrhosis." (PMID 35059422, 2021).
liver fibrosis (1 paper, 2021). "To confirm the diagnostic performance of autoantibodies for liver fibrosis staging, we selected autoantibodies to CENPF and ACY1 for further examination by ELISA based on the protein microarray results and our previous studies." (PMID 35059422, 2021). "Owing to lack of availability of HSPA6 protein, we only validated the diagnostic performance of autoantibodies to CENPF and ACY1 for liver fibrosis staging by ELISA." (PMID 35059422, 2021). "The diagnostic performance of CENPF and ACY1 autoantibodies for staging liver fibrosis tested by ELISA." (PMID 35059422, 2021). "In the present study, the results of the protein microarray showed that autoantibodies to CENPF, ACY1, ENO1, and HSPA6 may have underlying detection values for liver fibrosis staging." (PMID 35059422, 2021). "The relative titers of CENPF and ACY1 autoantibodies in patients with different stages of liver fibrosis were significantly higher than those in healthy controls." (PMID 35059422, 2021). "Comparison of the positivity rate of autoantibodies against CENPF, ACY1 and the two autoantibodies combined between different stages of liver fibrosis showed significant differences between S4 and S0-1, S4 and S2-3, S4 and S0-3, S2-4 and S0-1." (PMID 35059422, 2021). "CENPF and ACY1 autoantibodies had area under the curve values of 0.746 and 0.685, 58.14 and 74.42% sensitivity, and 88.41 and 60.87% specificity, respectively, for discriminating liver fibrosis stages S4 and S0-1." (PMID 35059422, 2021). "CENPF and ACY1 autoantibodies had AUC values of 0.746 and 0.685, sensitivity of 58.14 and 74.42%, and specificity of 88.41 and 60.87%, respectively, for discriminating liver fibrosis stages S4 and S0-1." (PMID 35059422, 2021). "The prevalence of CENPF and ACY1 autoantibodies was not correlated with age, sex or the level of inflammation, suggesting that these autoantibody biomarkers may be independent predictive factors for liver fibrosis." (PMID 35059422, 2021).
lymph node metastasis (1 paper, 2020). "A study showed the upregulation of CENPF was linked to cancer progression and lymph node metastasis." (PMID 33272232, 2020).
meningioma (1 paper, 2007). A generally slow growing tumor attached to the dura mater. "In addition, we found induction of IGFBP3, CENPF, CKS2 and reduction of LTBP2, PTPRF in high-grade meningiomas as previously reported." (PMID 17937814, 2007).
neuroblastoma (1 paper, 2014). Neuroblastoma (NB) is the most common solid, extracranial childhood tumor. "A majority of FOXM1 target genes, including CDC25B, CHEK2, CENPA, CENPB, and CENPF, were significantly downregulated in neuroblastoma cells with MEIS2 depletion." (PMID 25210800, 2014).
non-small cell lung adenocarcinoma (1 paper, 2018). Type of epithelial lung cancer arising from glandular origin. "In support of our findings, recent evidence shows CENPF siRNA knockdown resulting in cisplatin resistance in a variant small cell lung carcinoma and a non-small cell lung adenocarcinoma." (PMID 29618387, 2018).
non-small cell lung carcinoma (1 paper, 2025). A group of at least three distinct histological types of lung cancer, including non-small cell squamous cell carcinoma, adenocarcinoma, and large cell carcinoma. "In breast, adrenocortical, cervical, ovarian, and non-small-cell lung cancers, aberrant expression of CENPF has been observed." (PMID 40564876, 2025).
sarcoma (1 paper, 2023). A usually aggressive malignant neoplasm of the soft tissue or bone. "In addition, the potential association of CENPF and its co-expressed genes with therapeutic drug sensitivity in sarcoma was estimated by drug sensitivity analysis through GSCALite platform." (PMID 37108172, 2023). "The graph revealed that CENPF and its co-expressed genes displayed a significant association with drug sensitivity of Trametinib, selumetinib and RDEA119 for sarcoma treatment." (PMID 37108172, 2023). "Then, the relationship between CENPF expression and the infiltration levels of immune cells was evaluated in sarcoma." (PMID 37108172, 2023). "According to TIMER, the expression level of CENPF was positively correlated with tumor purity or the infiltration level of B cells, while negatively correlated with the infiltration level of CD4+ T cells or macrophages in sarcomas." (PMID 37108172, 2023).
serous ovarian cancer (1 paper, 2021). "This showed that higher expressions of CDCA3, CENPF, NCAPG, RRM2, UBE2C, and NBEA were associated with worse OS regardless of serous ovarian cancer stages." (PMID 34577856, 2021).
tumor (106 papers, 2008 to 2026). "CENPF is also overexpressed in a variety of malignancies and is associated with aggressive tumor characteristics and prognosis." (PMID 36984548, 2023). "MiR-1-3p targeting CENPF affects the tumor microenvironment through infiltrating interactions with tumor-associated inflammation, macrophages, mast cells, dendritic cells, and B cells." (PMID 36260870, 2022). "Then, Kaplan-Meier analyses of CENPF were performed to show that high expression levels of CENPF in tumor were significantly associated with the deterioration of OS and PFS in HCC patients." (PMID 33854594, 2021). "As a cell cycle-associated nuclear antigen, CENPF is involved in chromosome segregation during mitosis, and found to be related to tumor growth in many human malignancies." (PMID 33061942, 2020). "CENPF overexpression is positively associated with an advanced differentiation stage and a shorter overall survival, making it a risk factor for the cancer prognosis related to the ability of tumor cell proliferation and migration." (PMID 36661515, 2023). "This suggests that CENPF overexpression may be closely associated with the malignancy of LPS and contribute to the accelerated tumor progression." (PMID 37108172, 2023). "It is also possible that LPS-induced enhanced proliferation in tumor enteroids was caused by the increased expression of genes involved in the cell cycle process such as centromere protein F (CENPF) and flap endonuclease GEN homolog 1 (GEN1) as well as a receptor protein tyrosine kinase (STYK1)." (PMID 35884586, 2022). "First, we found the co-overexpression of FOXM1 and CENPF in HCC was associated with aggressive tumor behavior, including the presence of venous invasion, tumor microsatellite formation, and the absence of tumor encapsulation by clinicopathological correlation analysis." (PMID 35865168, 2022). "High expression of CENPF is associated with larger tumor size and poorer survival in NSCLC." (PMID 34307447, 2021). "Additionally, in some cases CENPF expression is associated with aggressive tumor phenotype and poor survival." (PMID 32973403, 2020). "Interestingly, the oncogenic activity of these genes (excluding FAM82B) was highly correlated with gene-copy numbers in tumor samples (correlation coefficient, r>0.423), indicating that amplifications of CENPF, GMNN, and CDK13 genes are tightly linked and coincident in tumors." (PMID 22912832, 2012). "Overexpression of CENPF in BCa correlates with poor prognosis, and miR-205-5p-mediated suppression of CENPF expression inhibits tumor growth." (PMID 40519684, 2025). "Thirty days after tumor implantation, we observed that CENPF knockdown significantly inhibited tumor growth as measured by tumor volume and weight." (PMID 40299364, 2025). "The discovery that CDK1, TOP2A, AURKA, TPX2, BUB1B, and CENPF are key cell-cycle regulators in NSCLC emphasizes the ongoing contribution of mitotic dysregulation to tumor growth." (PMID 41080754, 2025). "In vivo assays also showed CENPF downregulation significantly weakened tumor growth and metastasis and that CENPF expression was positively correlated in tumor tissue with Ki67, which is a widely accepted biomarker for cell proliferation." (PMID 40299364, 2025). "This multimodal approach exploits the synergistic effects of cisplatin's DNA crosslinking and miR-205-5p's gene-silencing capability to downregulate CENPF, disrupting key processes in tumor cell division and proliferation." (PMID 40519684, 2025). "As a result, CENPF expression was significantly higher in LPS tissue compared to the adjacent non-tumor control (adipose tissue) (p < 0.0001)." (PMID 37108172, 2023).
tumor (continued). "The tumor mutation burden (TMB) of these genes was also analyzed, and ASPM, CENPF, and POLQ had higher mutation rates than the other genes." (PMID 37077308, 2023). "In tumor migration, hnRNPR directly interacts with CCNB1 and CENPF mRNA to contribute to tumor malignancy and poor outcomes in cancer patients." (PMID 37479693, 2023). "Previous studies on CENPF have mainly focused on kinetochore function, tumour proliferation and metastasis." (PMID 36720923, 2023). "Inhibition of CENPF distinctly reduced adhesion between tumor cells and matrix and cell invasion in human SW13 cells." (PMID 35123514, 2022). "Upon clinicopathological correlation, we found that co-overexpression of CENPF and FOXM1 in human HCCs was associated with more aggressive tumor behavior including presence of venous invasion, tumor microsatellite formation, and absence of tumor encapsulation." (PMID 35865168, 2022). "It showed that interference of CENPF inhibited the cell proliferation, adhesion between tumor cells and matrix, cell migration, cell invasion, and the G2/M-phase transition, while remarkably enhancing cell apoptosis of SW13 cells." (PMID 35123514, 2022). "Then Western blotting was used to test the protein expression levels of FOXM1, Cyclin B1 and CENPF in tumour tissues, the results showed that the protein expression were inhibited by SH3PXD2A-AS1 knockdown." (PMID 35410446, 2022). "Even though LPS treatment failed to diminish the expression of genes involved in proliferation and malignancy such as GEN1, KRIT1, CENPF, STYK1, and Sam68/KHDRBS3, it did reduce the expression of numerous genes implicated in tumor growth." (PMID 35884586, 2022). "And, overexpressed Centromere Protein F (CENPF) is closely related to the oncogenesis of various neoplasms, including ACC." (PMID 35123514, 2022). "At 24 to 96 h post-10 Gy the percentage of CENPF positive tumor cells in the OB was significantly greater than in RH indicating an increase in G2 cells in OB as compared to those in the RH by 24 h after irradiation." (PMID 36482431, 2022). "The TIMER database was utilised to evaluate the correlations of the CENPF expression with the tumor infiltering immune cells and the known EGFR-TKI resistance related genes." (PMID 35154456, 2022). "As an alternative method for G2 phase analysis and to avoid tissue disaggregation, levels of the G2 specific protein CENPF were determined with Sox2 co-staining to identify tumor cells." (PMID 36482431, 2022). "In this study, we found that CENPF expression level in LUAD tissues was significantly elevated than adjacent non-tumor lung tissues using clinical samples." (PMID 33390818, 2021). "This study aimed to determine the role of CENPF in tumor growth and aggression in both clinical LUAD tissues and human LUAD cell lines." (PMID 33390818, 2021). "Further survival analyses, ROC curve analysis and representative image analysis, selected 5 hub genes, including CDK1, CDC20, CCNB1, CENPF, and MAD2L1, that were associated with early diagnosis, tumour stage, and poor outcomes of HCC." (PMID 34603487, 2021). "The relationship between the transcription levels of CENPF and the tumor stage/grade in HCC patients were also analyzed by the GEPIA and TCGA dataset." (PMID 33854594, 2021). "The tumor size and weight of the CENPF-Knockdown+Fulvestrant group were significantly lower than CENPF- Negative Control +Fulvestrant group (P=0.001, 0.039) in nude mice." (PMID 33428600, 2021). "As a novel therapeutic target, CENPF has been found to be overexpressed in various cancers and related with aggressive tumor phenotype as well as poor prognosis in different cancers." (PMID 33390818, 2021).
tumor (continued). "Taken together, these results indicated that the knockdown of CENPF significantly inhibited the tumor growth of the LUAD cells in vitro and in vivo." (PMID 33390818, 2021). "We have discovered four genes of prognostic value (CENPF, FOXM1, MCM4, and TOP2A), and further prioritized MCM4 as a key biomarker of LPS associated with tumor invasiveness (tumor stage, grade, and Ki67 labeling index) and prognostication." (PMID 34178990, 2021). "Incidence of new tumor events after initial treatment was higher in CENPF high group than those in CENPF low group (P = 0.038)." (PMID 33854594, 2021). "For the pathways distribution from the KEGG database (c2.cp.kegg.v7.0), ASPM, CENPF, and PRC1 shared three important tumor-associated terms (KEGG_CELL_CYCLE, KEGG_OOCYTE_MEIOSIS, and KEGG_SPLICEOSOME) in the top five significant pathways." (PMID 33946043, 2021). "It was apparent that mRNA and protein expression levels of CENPF were significantly increased in patients with HCC and were manifestly associated with the tumor stage of HCC." (PMID 33854594, 2021). "As results, the mRNA expression level of CENPF was significantly and positively correlated with the tumor stage and grade for HCC." (PMID 33854594, 2021). "CENPF, BUB1, BUB1B, KIF23 and TTK were identified as the key potential genes affecting hypoxia associated tumor stemness in this study." (PMID 33148251, 2020). "Using GEPIA2, a web server integrating TCGA and the GTEx data for 33 cancer types, we found that TOP2A and CENPF expression are higher in tumor than normal tissues in most of cancer types except for LAML, which showed opposite trend for both MRs." (PMID 33023625, 2020). "Top hub genes of the black (M7) module BUB1B and CENPF are reported to contribute to the tumor microenvironment." (PMID 31628349, 2019). "The oncogenic activity of hnRNPR was dependent on its ability to stabilize the mRNA of CCNB1 and CENPF, which are key mediators of cell cycle and tumor metastasis, respectively." (PMID 31527303, 2019). "After 6 days the proliferative potential of the cells inside the tumor material was determined by measuring nuclear CENPF positivity and 24 h EdU incorporation." (PMID 26279295, 2016). "Together, these results indicated that CENPF functioned as a tumor promoter in CRC metastasis." (PMID 39922805, 2025). "Collectively, these findings indicate a tumor-promoting role of CENPF in CRC." (PMID 39922805, 2025). "Additionally, centromere protein F (CENPF) has been shown to promote tumor metastasis and angiogenesis through the FAK/MAPK signaling pathway." (PMID 41341850, 2025). "Likewise, CENPF protein expression was significantly higher in CRC patients with tumor recurrence as demonstrated by representative immunostaining." (PMID 39922805, 2025). "Besides studying its expression changes during the cell cycle, several studies have investigated CENPF’s function during cell mitosis and tumor progression." (PMID 40299364, 2025). "In vivo, CENPF silencing reduced tumor growth and lung metastasis." (PMID 40299364, 2025). "hnRNPR stabilizes CCNB1 and CENPF mRNA to promote tumor metastasis." (PMID 37479693, 2023). "Univariate analysis showed that CENPF expression (p = 0.012, HR = 3.112, 95%CI [1.280–7.565]), new tumor status after treatment (p = 0.001, HR = 4.331, 95%CI [1.800–10.421]) and cancer status (p = 0.010, HR = 4.987, 95%CI [1.479–16.814]) were significantly associated with the OS of LPS patients." (PMID 37108172, 2023). "In conclusion, CENPF may be considered as a promising biomarker regarding LPS prognosis as well as tumor immune infiltration and may be a molecular therapeutic target for LPS patients." (PMID 37108172, 2023). "In short, these results suggested that the potential influences of CENPF on LPS progression may involve CENPF-mediated regulation of the cell cycle, thereby promoting tumor cell proliferation." (PMID 37108172, 2023).